RUNX2 (RUNX family transcription factor 2)
Diseases named in the same sentence as RUNX2 in open-access papers (continued):
Sharing a sentence is not in itself a finding about the gene and the disease.
colon carcinoma (22 papers, 2011 to 2026). "In human colon carcinoma, RUNX2 is associated with Dukes’ stage, liver metastasis, and ERβ status, and increases in these factors are related to adverse clinical outcomes." (PMID 36897488, 2023). "A recent study has reported that genetic variants in the TGFB1 pathway related genes (MAPK1, RUNX1 and RUNX2) are associated with CIMP-high colon cancer." (PMID 21949851, 2011). "Therefore, this study aimed to elucidate the effects of ethanol extracts of LT (ELT) relative to the role of Runx-2 in the metastatic and invasive potentials of mouse colon cancer CT-26 cells and to reveal the underlying mechanisms involved." (PMID 30105080, 2018). "Likewise, in colon cancer, RUNX2 has been significantly associated with Dukes staging, liver metastasis, and ERβ status." (PMID 28061442, 2017). "In colon cancer cells, invasion and migration levels are positively regulated by RUNX2 and Brahma-related gene 1 (BRG1) which form a complex regulating cluster of differentiation 44 (CD44) signaling pathway." (PMID 41511334, 2025). "In a colon cancer study, RUNX2 was found to trigger epithelial–mesenchymal transition (EMT) in vitro through orchestration of the chromatin landscape and the expression of EMT-related genes." (PMID 37108164, 2023). "In an exploration of clinical data in colon cancer, RUNX2 was expressed higher in cancer patients with metastasis and shorter survival." (PMID 37108164, 2023). "This regulatory relationship was also observed in colon cancer cells, where RUNX2 works downstream of Wnt signaling to facilitate the EMT process." (PMID 36429115, 2022). "By blocking the expression of ERβ by gene silencing or with a protein-level inhibitor, a reduction in RUNX2 levels in vitro, as well as a reduction in the proliferation of these colon cancer cells, were shown." (PMID 32722068, 2020). "In colon cancer, RUNX2 was suggested as an unfavorable prognostic factor that promotes the proliferation and invasion of tumor cells through an estrogen signal pathway." (PMID 27007162, 2016). "SiRNA-mediated knockdown of RUNX2 in human colon carcinoma cells leads to decreased migration and invasion." (PMID 26204939, 2015). "RUNX2 expression levels in colon carcinoma tissues were higher than in normal tissues." (PMID 37446127, 2023). "RUNX2 was further found to elicit the metastasis of colon cancer cells in vivo." (PMID 37108164, 2023). "Moreover, relatively high co-expression scores were also observed for RUNX2/ETS1, RUNX2/FOXO3, HNF1B/HNF4A, and HNF1B/FOXA3, suggesting that the DETFs associated with DARs might work together and be responsible for 5-FU resistance in colon cancer cells." (PMID 35252200, 2022). "Besides, from in vitro analyses of colon cancer cells, i.e., SW480 and DLD1, RUNX2 gene silencing experiments showed a reduction in the proliferation, migration and invasion of cells compared to control cells." (PMID 32722068, 2020). "Moreover, relatively high coexpression scores were also observed for FOSL2/KLF6, FOSL2/RUNX2 and GRHL2/FOXA1, suggesting that the DETFs related to H3K23su DERs might work together and be responsible for 5-FU resistance in HCT15 colon cancer cells." (PMID 40082673, 2025).
gastric cancer (22 papers, 2007 to 2025). A primary or metastatic malignant neoplasm involving the stomach. "MGAT5, MMP13, and RUNX2 were significantly positively associated with each other in gastric cancer based on the GEPIA database." (PMID 37256183, 2023). "RUNX2 has been proposed as a diagnostic biomarker for gastric cancer patients and is positively related to poor clinical prognosis and a range of clinicopathological characteristics." (PMID 37256183, 2023). "Runt-associated transcription factor 2 (RUNX2) has been found to be overexpressed in gastric cancer and facilitate the invasive and metastatic properties of gastric cancer cells." (PMID 37256183, 2023). "This study aimed to elucidate the role of RUNX2 in the invasive and metastatic potentials of human gastric cancer (GC) and the underlying mechanisms." (PMID 27007162, 2016). "Runx2 expression was associated with differentiation and invasion of gastric cancer." (PMID 35342401, 2022). "In contrast to the other RUNX family members such as RUNX1 and RUNX3 whose mutations are tightly linked to the promotion of leukemia and gastric cancer, respectively, the initial studies strongly suggest that RUNX2 acts as a master regulator of osteoblast differentiation and bone development." (PMID 29558908, 2018). "RUNX2 has been reported to be a novel prognostic signature and correlate with immune infiltrates in bladder cancer, cervical cancer and gastric cancer." (PMID 39822248, 2024). "Together, these findings confirmed that RUNX2 knockdown inhibited gastric cancer tumor growth in mice." (PMID 37256183, 2023). "Here, we elucidated the role of RUNX2 in the tumorigenesis of gastric cancer cells using the GEPIA database." (PMID 37256183, 2023). "In a clinical study of gastric cancer, patients with positive RUNX2 expression had unfavorable survival, clinical stage, and associated lymph node metastasis." (PMID 37108164, 2023). "The regulation of RUNX2 toward the extracellular matrix component collagen type I alpha 1 (COL1A1) was revealed in a gastric cancer study." (PMID 37108164, 2023). "We found that RUNX2 is highly expressed in gastric cancer cell lines, the silencing of which impaired gastric cancer growth and metastasis." (PMID 37256183, 2023). "Collectively, these results demonstrated that the knockdown of RUNX2 suppressed the proliferation, invasion and migration abilities of gastric cancer cells." (PMID 37256183, 2023). "Previous studies have highlighted COL1A1, YAP1 and chemokine receptor CXCR4 as targets of RUNX2 that facilitate the in vitro invasion and metastatic potential of gastric cancer cells." (PMID 37256183, 2023). "RUNX2 is overexpressed in gastric cancer but the mechanism(s) through which it promotes tumor progression remain undefined." (PMID 37256183, 2023). "In vivo assays confirmed the aberrant expression of RUNX2 in mouse models of gastric cancer and reduced growth and lung metastasis in RUNX2 silenced xenograft tumors assessed." (PMID 37256183, 2023). "Consistent with previous studies, we observed high RUNX2 expression in gastric cancer cells which promoted MMP13 and MGAT5 expression." (PMID 37256183, 2023). "Previous studies have shown that RUNX2 is overexpressed in gastric cancer cells and acts to promote their invasion and metastatic capacity." (PMID 37256183, 2023). "In vivo assay was used to evaluate tumor growth, aberrant expression of RUNX2 and lung metastasis of gastric cancer." (PMID 37256183, 2023). "In summary, we identify MGAT5 and MMP13 as novel RUNX2 targets with known metastatic potential in gastric cancer cells and tissue." (PMID 37256183, 2023).
gastric cancer (continued). "On the other hand, RUNX2 positively regulates the YAP signaling pathway in gastric cancer cells, and the activation of YAP1 promotes CC." (PMID 35805994, 2022). "RUNX2 was found to be involved in the maintenance of self-renewal properties and malignant potential in gastric cancer cell lines." (PMID 34831147, 2021). "An analysis of gastric cancer patients revealed elevated RUNX2 expression in early cancer stages and high RUNX2 expression correlated with poor prognosis." (PMID 34831147, 2021). "Ectopic expression of RUNX2 in gastric cancer cell line MGC803 correlated with increased YAP expression, while depletion of RUNX2 in XN0422 reduced the YAP mRNA expression." (PMID 34831147, 2021). "We found that the levels of RUNX2 expression in gastric cancer tissues were correlated with the differentiation degrees, invasion depth and lymph node metastasis." (PMID 27007162, 2016). "Moreover, upregulated RUNX2 in gastric cancer also promotes gastric cancer progression through transcriptional activation of MGAT5 and MMP13." (PMID 38430423, 2024). "In gastric cancer, RUNX2 expression levels were analyzed by immunohistochemical staining of 60 cancer tissues and by consulting the Gene Expression Profiling Interactive Analysis (GEPIA) database, which demonstrated the high expression of RUNX2 at both the gene and protein levels in gastric cancer." (PMID 37108164, 2023). "In addition to regulating cell proliferation, RUNX2 promotes the self-renewal of gastric cancer cells and aids in tumor invasion and metastasis." (PMID 37370857, 2023). "Here, we investigated the role of RUNX2 on gastric cancer pathogenesis at the molecular level." (PMID 37256183, 2023). "We next examined whether the effects of RUNX2 on gastric cancer cells were mediated by the overexpression of MMP13 and MGAT5." (PMID 37256183, 2023). "Runx2 is an independent prognostic marker in gastric cancer." (PMID 35342401, 2022). "In another gastric cancer study, RUNX2 was found to promote metastasis through the upregulation of COL1A1 expression, with patients displaying elevated levels of both RUNX2 and COL1A1 experiencing reduced survival times, thereby indicating a poor prognosis." (PMID 38430423, 2024). "Collectively, these data reveal that RUNX2 enhances MGAT5 and MMP13 expression in gastric cancer cells and represents a biomarker and potential therapeutic target for gastric cancer therapy." (PMID 37256183, 2023). "Together, these data revealed a role for RUNX2 in independently regulating the expression of MGAT5 and MMP13, the RUNX2/MGAT5/MMP13 positive axis in gastric cancer." (PMID 37256183, 2023). "In this study, it was uncovered that RUNX2 activates the transcription of MGAT5 and MMP13 which act to facilitate gastric cancer metastasis in vitro and in vivo." (PMID 37256183, 2023). "RUNX2 has been shown to enhance NID1 signaling, and promote malignant progression in gastric cancer by regulating COL1A1, YAP1 and FN1 expression." (PMID 37256183, 2023). "RUNX2 expression in human gastric mucosal epithelial cell line (GES-1) and gastric cancer cell lines (MKN-45 and AGS) was investigated via qRT-PCR and western blotting." (PMID 37256183, 2023). "B RUNX2 mRNA and protein levels were both highly expressed in MKN-45 and AGS cells, confirming that RUNX is upregulated in gastric cancer, consistent with previous studies." (PMID 37256183, 2023). "This highlights RUNX2, MGAT5 and MMP13 as key biomarkers of metastatic gastric cancer and therapeutic targets for much-needed anti-gastric cancer drugs." (PMID 37256183, 2023). "Analysis of the gastric cancer samples from the database revealed a significant positive correlation between MGAT5, MMP13, and RUNX2 expression." (PMID 37256183, 2023). "In gastric cancer, JQ1 downregulates chromatin accessibility and inhibits the RUNX2/NID1 signaling pathway, thereby preventing gastric cancer progression." (PMID 35965507, 2022).
gastric cancer (continued). "In a sharp contrast to RUNX2, it has been shown that RUNX3 is recruited onto the putative RUNX3-binding sites of VEGF promoter, trans-represses its transcription, and suppresses gastric cancer angiogenesis." (PMID 29558908, 2018). "We further found that the effects of RUNX2 are mediated through the activation of MGAT5 and MMP13 both in vitro and in vivo, as their overexpression could compensate for RUNX2 depletion in gastric cancer cell lines and xenograft tumor models." (PMID 37256183, 2023). "Hence, our experiments were conducted to investigate the relationships among RUNX2, MGAT5 and MMP13 in gastric cancer." (PMID 37256183, 2023). "Induction of only RUNX3 at unaffected RUNX2 was observed after BMP stimulation of the human gastric cancer cell line HT-29, corroborating the non-redundant regulation of RUNX2 and RUNX3 expression by BMP signaling." (PMID 32195247, 2020). "In gastric cancer cell lines, BRD4 inhibition did not alter RUNX2 expression itself, however BRD4 was required for maintenance of open chromatin at RUNX2 binding sites in the genome." (PMID 38063851, 2024).
atherosclerosis (20 papers, 2016 to 2025). A disease characterized by the build-up of fatty material and calcium deposition in the arterial wall resulting in partial or complete occlusion of the arterial lumen. "In atherosclerosis, OMVs from P. gingivalis have been shown to induce foam cell formation, promote platelet aggregation, suppress eNOS, and activate RUNX2-mediated vascular calcification, through well-characterized ROCK and MAPK signaling pathways." (PMID 40791780, 2025). "OMVs also activate the ERK1/2 and runt-related transcription factor 2 (RUNX2) signaling pathways in vascular smooth muscle cells, promoting calcification and accelerating atherosclerosis." (PMID 40791780, 2025). "Mounting evidence indicates that ubiquitin-mediated proteasomal degradation of RUNX2 and subsequent modification of RUNX2 protein levels play pivotal roles in multiple pathogenesis of calcification procedures, such as, skeletal development and atherosclerosis." (PMID 36774349, 2023). "Next, we analyzed the datasets (GSE43292, GSE12644, and GSE83453) obtained from aortas isolated from patients with atherosclerosis and stenosis for Cdon expression, together with aortic calcified markers such as Runx2, ALPL (alkaline phosphatase), and CD68." (PMID 36609601, 2023). "It has been demonstrated that Sirt1 insufficiency may induce the calcification and atherosclerosis in cardiovascular tissues, through a mechanism involving upregulation of Runt-related transcription factor 2 (Runx2), which is the osteogenic transcriptional activator." (PMID 27367673, 2016). "Vascular calcification is an essential stage in atherosclerosis, whereby vascular smooth muscle cells (VSMCs) synthesise many osteogenic factors such as bone sialoprotein (BSP) and runt-related transcription factor 2 (Runx2)." (PMID 39769058, 2024). "BMP2, ERK/MAPK, and PI3K/AKT signaling pathways induce RUNX2 expression in VSMC, promoting vascular calcification and atherosclerosis while pharmacological inhibition or degradation of RNUX2 can reduce calcification." (PMID 36923537, 2023). "Runt-related transcription factor 2 (Runx2), a key osteogenic regulator, regulates VSMC osteogenic differentiation and vascular calcification in atherosclerosis." (PMID 35004893, 2021). "During atherosclerosis, activation of autophagy in the ECs induces packing and secretion of miR-204-5p; this targets BCL2 when absorbed by the ECs and runt-related transcription factor 2 (RUNX2) when absorbed by the VSMCs to alleviate smooth muscle cell calcification." (PMID 40823532, 2025). "Genetic defects in AMPKα1 but not AMPKα2 promote atherosclerosis calcification and Runt-related transcription factor 2 (Runx2) expression." (PMID 32457625, 2020).
hepatocellular carcinoma (17 papers, 2007 to 2025). A malignant tumor that arises from hepatocytes. "In hepatocellular carcinoma, elevated RUNX2 expression is likewise associated with shorter survival times." (PMID 38430423, 2024). "Since the RUNX2 transcription regulator is implicated in many signalling pathways and interacts with multiple regulatory molecules like microRNAs and lncRNAs, more in-depth studies to clarify its role in the molecular pathology of hepatocellular carcinoma are needed." (PMID 37759525, 2023). "A recent study also demonstrated that RUNX2 transcriptionally activates ITGBL1 in hepatocellular carcinoma, contributing to immune evasion in the tumor microenvironment." (PMID 40287769, 2025). "RUNX2, a unique transcription factor, exhibits a crucial oncogenic role in hepatocellular carcinoma." (PMID 37759525, 2023). "In the examination of 89 human hepatocellular carcinoma samples, RUNX2 expression appeared to correlate with vasculogenic mimicry (VM), the mimicry of endothelial cells by cancer cells to form the microvascular structure in aggressive tumors." (PMID 37108164, 2023). "The level of RUNX2 expression significantly correlates with the expression level of MMP9 in hepatocellular carcinoma." (PMID 37759525, 2023). "In hepatocellular carcinoma, the data from clinicopathological analysis of 89 samples indicated the correlation of RUNX2 expression with metastasis rate and shorter survival period." (PMID 37108164, 2023). "In caveolin-1-dependent hepatocellular carcinoma invasion, RUNX2 expression appeared to be suppressed by caveolin-1 along with the repression of RUNX2-induced miR24 transcription." (PMID 37108164, 2023). "In another study on mouse hepatoma cells, RUNX2 binds to the miR-23a gene’s promoter and indirectly promotes lymphatic metastasis by targeting the Mgat3 glycosyltransferase directly affecting the glycosylation process on the cell surface." (PMID 37759525, 2023). "RUNX2 expression appeared to be repressed by caveolin-1, a major structural protein of caveolae; the RUNX2-induced transcription of miR24 was attenuated during caveolin-1-mediated cell invasion in hepatocellular carcinoma." (PMID 37108164, 2023). "Moreover, aberrant RUNX2 expression could be an independent prognostic factor since hepatocellular carcinoma patients with high RUNX2 expression demonstrated shorter 5-year disease-free and overall survival." (PMID 37759525, 2023). "In another study, RUNX2 and transcriptional regulator YAP inhibit the expression level of lncRNA annotated MT1DP, demonstrating tumour-suppressive behaviour in hepatocellular carcinoma." (PMID 37759525, 2023). "Runx2 plays a key role in EMT of hepatocellular carcinoma (HCC)." (PMID 31766574, 2019). "In summary, our findings identify Runx2 as a transcriptional activator of miR-23a and demonstrate that as an oncogene, miR-23a may promote lymphatic metastasis by targeting Mgat3, which regulates the branching pattern of N-glycans on the mouse hepatoma cell surface." (PMID 29743543, 2018). "However, the relationship between Runx2, Galectin-3, EMT, and VM has not been studied in hepatocellular carcinoma (HCC)." (PMID 28264434, 2017).